APC (APC regulator of Wnt signaling pathway)
Diseases named in the same sentence as APC in open-access papers (continued):
Sharing a sentence is not in itself a finding about the gene and the disease.
cancer (continued). "DDR and related genes were found frequently methylated in human cancers, including BRCA1/2, MGMT, WRN, MLH1, CHFR, P16 and APC." (PMID 32974031, 2020). "Taken together, our results demonstrated that the inactivation of APC in PDAC promotes cell proliferation and EMT and increases cancer cell migratory ability in vitro." (PMID 32586050, 2020). "By comparing the genomic alteration of 20q13.33 gain with APC and KRAS mutations (62.63% vs 42.93 and 23.73%, respectively), which are currently identified as the most important targets for CRC therapy, the results support that 20q13.33 gain may have been involved in the development of cancer." (PMID 33087131, 2020). "CDK2 is mainly involved in the APC cell cycle regulation pathway, and the overexpression of CDK2 results in the upregulation of the G1/S phase transition, resulting in cancer cell proliferation." (PMID 31921802, 2019). "Promoter methylation of six genes (APC, CCND2, FOXA1, PSAT1, RASSF1A, and SCGB3A1) in ctDNA in breast cancer patients was confirmed as cancer-specific, although with a variable performance." (PMID 31752198, 2019). "Tumor suppressor genes, such as RASSF1A, APC, PRKCDBP, and P16, are reported to be involved in the regulation of placentation and that their silencing is crucial for human cancer development." (PMID 31752198, 2019). "The APC mutant clone had also developed an ARID1A mutant subclone (ARID1A detected in a single region of carcinoma)." (PMID 29991641, 2019). "Subgroup meta-analysis by geographical populations was performed for p16, RASSF1A, GSTP1, APC and RUNX3 between HBV-positive carcinoma tissues and HBV-negative carcinoma tissues." (PMID 31772678, 2019). "Our results showed six genes (p16, RASSF1A, GSTP1, APC, p15 and SFRP1) in HBV-positive carcinoma tissues, one gene (GSTP1) in HBV-positive adjacent tissues and two gene (p16 and APC) in HBV-positive carcinoma serums, which were significantly hypermethylated." (PMID 31772678, 2019). "We selected circ-APC (hsa_circ_ 0127621) for further investigation because its expression differed the most between DLBCL and para-carcinoma tissues." (PMID 31631067, 2019). "Multiple key negative regulators, such as APC, GSK-3β, and Axin, are suppressed in cancer, contributing to the promotion of tumor progression through regulation of the Wnt/β-catenin pathway." (PMID 29304823, 2018). "On the other hand, higher expression of HRAS, NRAS, APC, HFE, MMP9, and a high enrichment of MAPK/RAS, NFKB, and TNF signaling pathways are all evident in HLE cells as often seen in cancer." (PMID 30176945, 2018). "APC and SCGB3A1 disclosed 100% specificity for cancer detection, whereas PSAT1 showed the highest sensitivity (91.97%)." (PMID 30405052, 2018). "Many gene mutations of the canonical WNT/β-catenin pathway giving rise to cancers have been reported (CTNNB1, AXIN, APC)." (PMID 29706964, 2018). "APC, FOXA1 and RASSF1A individually depicted sensitivity over 20% and specificity greater than 70%, for all cancers." (PMID 30261643, 2018). "There has been a mass of studies elaborating the significant relation of ANC, APC, ALC, NLR or PLR with prognosis in different types of cancers, as well as HNSCC." (PMID 29589142, 2018). "To investigate the role of PLK1 in cancer cells with CIN, we expressed in both cell lines a truncated APC protein containing amino acids 1-750 of APC, hereafter named APC-ΔC, thus removing all β-Catenin regulatory sequences." (PMID 29549256, 2018).
cancer (continued). "As for CRC, the significantly higher APC, FOXA1, RARβ2, RASSF1A, SCGB3A1, SEPT9 and SOX17 methylation levels in cancer patients are in line with previous publications, although divergent results have been reported for MGMT." (PMID 30261643, 2018). "MSH3, MSH6, APC and PIK3CA genes seem to play a bigger role in the path to cancer in this population." (PMID 28002797, 2017). "Others have reported similarly higher levels of S33/37/T41 pβ-catenin in the cancer cell line SW480, which carries a truncated form of APC." (PMID 28808228, 2017). "Recently, many epigenetic biomarkers have been studied in cancer diagnosis, including hMLH1, E-cadherin, CDKN2A, CDKN2B and APC in GC and SEPT9, SFRP2, THBD, SDC2, VIM and FBN1 in CRC." (PMID 29137404, 2017). "The results demonstrated that human miR-125b, which positively regulates EMT and wnt/β-catenin signaling by targeting APC expression, is controlled by CXCL12/CXCR4 signaling in cancer cells." (PMID 28176874, 2017). "An RNAi screen for factors whose depletion inhibits the growth of mutant KRAS G12D-expressing cancer cell lines identified PLK1 and components of the APC/C ubiquitin-conjugating holoenzyme." (PMID 28807782, 2017). "Notably, another study on cell cycle arrest experiments found that HSP70 specific inhibitor PES-Cl treatment could effectively inhibit cyclin B degradation and APC/C (anaphase promoting complex/cyclosome) activity, which always resulted in G2/M arrest in cancer cells." (PMID 28938577, 2017). "In addition, loss of APC and APC2 results in increased expression of the Wnt signaling target genes cMYC and Sox9, lending further weight to the clinical relevance of the loss of both genes, especially for a difficult to treat sub-population of human cancer patients." (PMID 27694902, 2017). "As model inhibitors, we used sFRP1 and Dkk1 and as model cells, we used known cell lines that mimic the level of LoF of APC in human cancer cells, both with truncated APC (APC1572T) and with attenuated levels of full-length APC (APCneoR, APCneoF)." (PMID 28708837, 2017). "Using bisulfite treatment followed by MS-PCR we detected methylation of the LRRC3B, APC, FHIT, and RASSF1 genes in the cfDNA of cancer patients." (PMID 27725787, 2016). "APC and the Wnt signaling target gene ITF2 (immunoglobulin transcription factor 2) incur hypermethylation in various cancers, however, methylation-dependent regulation of these genes in CRC has not been studied in large, well-characterized patient cohorts." (PMID 26884349, 2016). "Given the pivotal role of APC–Cdc20 in governing mitotic progression, blockade of chromatid segregation or mitotic exit largely attracts the attention for development of small molecule inhibitor that could be utilized to suppress cancer cell growth or induce cancer death." (PMID 27418942, 2016). "The method’s utility is highlighted by some well-known cancer genes such as CDK4, APC and EZH2 are only captured by GAP." (PMID 27296290, 2016). "Axin, β-catenin, Adenomatous polyposis coli (APC) and STAT3/5 is the integral component of the Wnt/β-catenin signaling pathway which plays a critical role in cell growth, differentiation and cancer process." (PMID 27613831, 2016). "The first group of genes presented higher methylation levels in cancer tissues than in blood DNA (CDKN2A, APC, and DAPK1)." (PMID 26338139, 2015). "These include the promoters of genes which have a well-established role in cancer progression such as RASSF1A, APC and E-cadherin, as well as completely novel sequences such as CAHM, a long non-coding RNA gene." (PMID 25988180, 2015).
cancer (continued). "Truncated mutations in APC that eliminate the AXIN-binding site result in human cancer, suggesting that the binding avidity of the AXIN protein for APC affects carcinogenesis." (PMID 26161041, 2015). "As such, the regions identified lie in the promoters of genes already well-defined as having a role in cancer, for example RASSF1A, APC and SOX17." (PMID 25988180, 2015). "GSK3β is a significant cancer control molecule; it controls the degradation of β-catenin by phosphorylating serine 33/37 of cytosolic β-catenin, and it may also be involved in crosstalk with the APC/CK1/Axin complex, which is important in cancer cell proliferation and metastasis." (PMID 24666969, 2014). "The second subgraph, which contains the largest number of component nodes, has its 95 nodes anchored to the known cancer proteins CTNNB1, APC, PTEN, TP63, MAPK4, MET, RAC1, and ROS1." (PMID 24516372, 2014). "Thus, it might be suggested that de novo cancers are also related to a variation of APC genetics." (PMID 23533795, 2013). "Promoter hypermethylation at MLH1, APC, RB1, VHL, MGMT, GSTP1, and BRCA1 represents paradigmatic cancer-related epigenetic silencing events." (PMID 22848209, 2012). "Only APC (39%), CCND2 (21%), CDH1 (7%), and RARB (4%) were hypermethylated in >2% of these cancer-free subjects." (PMID 21577262, 2011). "Equally, conditions thatlead to APC depletion or inactivation, such as HIV and cancer, would leave manyantigen-specific T cells undetected, due to the lack of properstimulation." (PMID 18670652, 2008). "In another study they applied a marker panel (APC, CDKN2A/p16, and RASSF1) to detect cancer in 247 patients, and reported 53% sensitivity and, in cases without a previous history of cancer, >99% specificity." (PMID 18947422, 2008). "We found that the concentrations of methylated APC, hMLH1 and TIMP3 were higher in patients with advanced stage cancer." (PMID 15942635, 2005). "Specifically, all three other genes found to be coordinately hypermethylated with GSTP1 in this study, APC, RARB2, and RASSF1A, are established as functionally important in other cancers." (PMID 15292941, 2004). "The APC gene, a tumor suppressor gene, plays an important role in the development of CRC by reducing or eliminating cell adhesion functions and promoting the infiltration and metastasis of cancer cells." (PMID 40521787, 2025). "Pan-cancer studies have revealed a higher frequency of recurrent alterations in cancer driver genes, including PIK3CA, APC, PTEN, and MYC, and higher overall burden of copy number alterations, including whole genome duplication in metastases compared with primary tumors." (PMID 39416100, 2025). "Emerging evidence suggests that APC/C and its co-activators (CDC20/CDH1) may influence cancer progression beyond cell cycle regulation, potentially through modulation of EMT and MMP pathways." (PMID 40136519, 2025).
cancer (continued). "Despite this, not all clinicians routinely determine the specific APC mutation in patients with FAP, as the diagnosis can be clearly established through sigmoidoscopy and the risk of cancer development is not influenced by knowledge of the mutation." (PMID 39370455, 2024). "Thus, APC/CCDH1 is likely the physiological E3 ubiquitin ligase for PIN1, and its activity is primarily inhibited by phosphorylation of CDH1 in cancer cells." (PMID 38622115, 2024). "Somatic genetic variations in APC, KRAS, BRAF, and PIK3CA genes are the most frequent in CRC, leading to the activation of key WNT–β-catenin and MAPK signal transduction pathways, which subsequently promote cell proliferation and cancer progression." (PMID 37863651, 2024). "We propose that a way to enhance the effectiveness of anti-cancer agents that increase multipolar spindles is by suppressing the APC/C-CDC20 to delay, but not block, anaphase entry." (PMID 38928036, 2024). "APC (P), BRCA2 (P), BUB1B (LP), ENG (LP) and MSH6 (P) were identified in patients with cancer." (PMID 36896836, 2023). "β-catenin binds transducin beta-like protein 1 (TBL1/TBLR1), and this complex stimulates the expression of several Wnt/APC/β-catenin pathway target genes, including proliferative factors, such as S100A4 or collagen triple helix repeat containing-1 (CTHRC1), identified as cancer-related proteins." (PMID 35913675, 2023). "Interestingly, pan-cancer analysis showed that MYC amplification is mutually exclusive with many canonical oncogenic drives such as PIK3CA, PTEN, APC, and BRAF." (PMID 37601651, 2023). "Pan-cancer analyses have shown that MYC is the 3rd most frequently amplified gene in malignant neoplasms, and its alterations are mutually exclusive with other genetic drivers like PIK3CA, PTEN, APC or BRAF." (PMID 37443779, 2023). "APC/CCDH1 is an E3 ligase that plays a central role in the cell cycle, especially at the G1 stage, and its tight regulation is crucial to preventing the development of diseases and cancer." (PMID 37176148, 2023). "Focussing on other cancer types, a study identified a negative correlation between APC expression and the expression levels of components of the translational apparatus in both breast and lung cancer." (PMID 37048063, 2023). "The most prevalent cancer genes were APC and SKI found across two cancer types." (PMID 37558831, 2023). "Although APC is associated with various types of cancer, no comprehensive analysis of APC in cancers has been conducted." (PMID 35303016, 2022). "Notably, as an activator of APC/C during mitosis, CDC20 is an important regulator of the cell cycle and plays a role in cancer emergence and development." (PMID 35804892, 2022). "Thus, it appears likely that the downregulation of KCTD9 occurs independently of such mutations and the effects of KCTD9 on β-catenin expression would still be relevant in APC and/or CTNNB1 mutant cancers." (PMID 36055981, 2022).
cancer (continued). "Among them, Apcin and pro-TAME have been identified as selective CDC20 and APC/CCDC20/APC/CCDH1 inhibitors, respectively, and are currently under preclinical investigation for their efficacy against different cancer subtypes, including hematological malignancies." (PMID 35490245, 2022). "Aberrant β-catenin immunostaining in cancer cells was observed in 9 out of 22 cases, of which 3 cases had the CTNNB1 mutation, one case had the APC mutation, and the remaining 5 cases had no mutations with Wnt pathway associated genes." (PMID 35778698, 2022). "K-756 and RK-287107 block cell growth in COLO-320DM and SW403 cancer cells, carrying a truncated form of APC lacking a short stretch of 20 amino acids involved in β-catenin binding." (PMID 34639169, 2021). "For example, Pik3ap1 displayed preferential loss of signal in the proximal 3′UTR in APC and APN cancer subtypes, uniform degradation in LPC cancer subtype, and no change in mature B cells." (PMID 34594359, 2021). "E3 ubiquitin ligases (Mule, SCFβ-TrCP, SCFFBW7, TRIM17, APC/CCdc20, and FBXO4) and deubiquitinases (USP9X, Ku70, USP13, JOSD1, and DUB3) work together to balance MCL1 stability, which has an important role in the chemoresistance of cancer cells." (PMID 33803505, 2021). "Of note, our sequencing panel does not include APC, which is an important cancer gene in the conventional pathway." (PMID 34712603, 2021). "In contrast, APC, DAPK1, IGSF4, RARB, and TIMP3 genes were found to be methylated in cancer cells." (PMID 34552632, 2021). "E3 ligases, or particular components of their complexes (MDM2, IAP, APC/CDC20, and others), are known as oncogenes or tumor suppressors in numerous types of cancer; thus, they may serve as potential cancer targets or are themselves “druggable” enzymes." (PMID 34502538, 2021). "Taken together, these findings suggest that regulation of NO and APC may occur simultaneously, and treatment strategies targeting these pathways may prevent WNT/B-catenin upregulation, preventing the development of cancer." (PMID 33513777, 2021). "Although Paclitaxel’s mechanism of action is well characterized, mechanisms of resistance remain vague, especially in cancers lacking APC." (PMID 34370741, 2021).